INS (insulin)
Diseases named in the same sentence as INS in open-access papers (continued):
Sharing a sentence is not in itself a finding about the gene and the disease.
Insulin resistance (continued). "The results showed that fasting blood glucose (FBG), fasting serum insulin (FINS), and homeostasis model assessment for insulin resistance (HOMA-IR) in diabetic liver injury mice were significantly decreased after punicalagin intervention." (PMID 35889739, 2022). "Baseline evaluation of homeostasis model assessment-insulin resistance (HOMA-IR), plasma glucose, insulin, leptin and adiponectin levels, and systolic and diastolic blood pressure (SBP and DBP) of patients was done." (PMID 35350513, 2022). "Lab analysis showed improvements for the melatonin group, including decreased homeostasis model of assessment-insulin resistance (HOMA-IR), serum insulin, total and LDL-cholesterol, and increased quantitative insulin sensitivity check index." (PMID 36235587, 2022). "There are several indicators of insulin resistance, including homeostasis model assessment of insulin resistance (HOMA-IR), homeostatic model assessment of β-cells (HOMA-β), and quantitative insulin sensitivity check index (QUICKI)." (PMID 36232291, 2022). "TNF-α is an adipocytokine involved in developing insulin resistance and the pathogenesis of T2DM by disrupting insulin signaling through serine phosphorylation." (PMID 36577761, 2022). "Insulin resistance is generally characterized by elevated plasma FFA levels, and elevated plasma FFA inhibits glucose transport in insulin-dependent cells and leads to hyperglycemia." (PMID 36145191, 2022). "Recently, the Metabolic score for insulin resistance (METS-IR), a newly-developed non-insulin-based metabolic score, consists of fasting plasma glucose (FPG), triglycerides (TG), high-density lipoprotein cholesterol (HDL-C), and body mass index (BMI)." (PMID 36992743, 2022). "Elevated values ​​of HOMA IR and elevated mean insulin value in OGTT confirm increased insulin secretion, hyperinsulinism, reduced insulin sensitivity and insulin resistance in patients with MS and pre-MS already in young obese individuals." (PMID 36685849, 2022). "On the other hand, some studies have demonstrated a significant improvement in insulin resistance and β-cell function in newly diagnosed T2DM patients treated with short-term intensive insulin therapy." (PMID 36421415, 2022). "The association still exists after adjusting for triglyceride (TG), fasting insulin (FI), fasting blood glucose (FBG), homeostasis model assessment of beta-cell function (HOMA-B) and insulin resistance (HOMA-IR), and glycated hemoglobin (HbA1c)." (PMID 36589806, 2022). "An excel spreadsheet from the University of Oxford was used to estimate HOMA scores; beta cell function, HOMA%B (%B), insulin sensitivity, HOMA%S (%S), and insulin resistance HOMA-IR (IR), based on glucose and plasma (P) C-peptide." (PMID 36013449, 2022). "In this study, Cori treatment attenuated HFD-induced increase of fasting blood glucose and insulin levels, and strongly reversed the HOMA-IR value, an index of systemic insulin resistance." (PMID 36071929, 2022). "Insulin sensitivity is enhanced by SIRT1 activation via reduction in the expression of proinflammatory genes and it attenuates the insulin resistance induced by tumor necrosis factor alpha (TNF-α)." (PMID 35163422, 2022). "Sustained SIAP2 consumption significantly decreased the insulin by − 5.25 mg/dL and HOMA-IR (homeostatic Model Assessment of Insulin Resistance) by − 1.33." (PMID 35643872, 2022). "Homeostasis model assessment of insulin resistance (HOMA-IR), which is calculated from FBG and fasting insulin, is used to being considered as the most recognized surrogate marker of IR." (PMID 36312238, 2022). "However, as we have shown here, measures of insulin-dependent-glucose uptake and adiposity are highly correlated and prior literature has shown that their association is complex and interactive: obesity engenders insulin resistance, but not all overweight or obese individuals are insulin resistant." (PMID 35492025, 2022).
Insulin resistance (continued). "To explore the effect of insulin resistance on glycolysis, we detected the expression of key glycolytic enzymes (HK2, PKM2, and LDHA) in KGN cells after insulin treatment and RES intervention." (PMID 36742000, 2022). "Most often this is accomplished by the Homeostatic Model Assessment for Insulin Resistance (HOMA-IR), which involves insulin-stimulated glucose uptake and/or glucose tolerance tests." (PMID 35884888, 2022). "Fasting glucose and insulin levels and HOMA-IR (homeostasis model assessment of insulin resistance) were appropriate for the degree of obesity when people carrying variants were compared to 2,138 controls of a comparable age, sex and BMI." (PMID 36536256, 2022). "One of the targets to induce insulin resistance and IRS-1 at a low ebb is viewed in obese and insulin-resistant individuals." (PMID 36235831, 2022). "The threshold homeostasis model assessment of insulin resistance (HOMA-IR) levels (calculated with the serum glucose and insulin concentrations) was much higher in the control group." (PMID 36552249, 2022). "Insulin resistance is a very common complication in PCOS patients, according to the WHO criteria for defining insulin resistance, about 75% of PCOS women have impaired insulin sensitivity." (PMID 36118901, 2022). "Fasting plasma glucose, insulin resistance index (HOMA-IR) and fasting plasma insulin in the patients seem to be comparable to those of lean controls." (PMID 35906625, 2022). "BMI, waist circumference, body weight, glucose, glycated haemoglobin (HbA1c), insulin, HIRI, and homeostatic model assessment of insulin resistance (HOMA-IR) were statistically significantly higher at baseline in the non-RE group than in the RE group." (PMID 36289459, 2022). "The findings on hemoglobin A1C (HbA1C), insulin, homeostasis model assessment of insulin resistance (HOMA-IR), β-cell function (HOMA-β), quantitative insulin sensitivity check index (QUICKI), and lipid profile were controversial." (PMID 35057819, 2022). "In turn, an inverse correlation between BMI and %ibw with glucose/insulin ratio and QUICKI and a direct correlation with HOMA index were found, indicating a linear correlation between body mass gain and insulin-resistance development." (PMID 35854365, 2022). "Applying a high-fructose diet, increased PCSK9 and insulin resistance were correlated, which is typically consistent with the increased HOMA-IR and insulin levels during Ramadan fasting." (PMID 35454343, 2022). "Obesity is a major determinant of insulin resistance and the development of T2DM, and only 10 to 25% of obese adults remain metabolically healthy and insulin-sensitive." (PMID 36187118, 2022). "Obese and insulin resistance patients in all KD groups showed reduction in BMI, body weight, waist circumference, blood pressure, HOMA index, insulin, and total LDL cholesterol." (PMID 36079829, 2022). "We would speculate that the late and high glucose peak, a slow post-peak decline of blood glucose in G4 indicated the risk of hepatic and peripheral insulin resistance, a weak first phase insulin secretion, and the lack of compensatory second phase insulin secretion." (PMID 36386904, 2022). "Insulin resistance (IR) was estimated by HOMA-IR and insulin sensitivity (IS) by reciprocal of fasting insulin." (PMID 35579861, 2022). "Primary measures were defined as metabolic or biochemical factors including fasting glucose, glycated hemoglobin (HbA1c) level, serum insulin, quantitative insulin sensitivity check index (QUICKI), Homeostatic Model Assessment for Insulin Resistance (HOMA‐IR)." (PMID 35243684, 2022). "Interestingly, some of the common ways of measuring insulin sensitivity are based on fasting insulin and glucose values such as homeostatic model assessment for insulin resistance (HOMA-IR), which may underestimate the role that physiologic insulin cycling plays in IR." (PMID 35163806, 2022).
Insulin resistance (continued). "Insulin and androgens work synergistically to reduce SHBG levels, resulting in higher free androgen levels, which aggravates the insulin resistance." (PMID 36140452, 2022). "Insulin resistance (IR) affects individuals for many years before the development of T2DM, and consists of a diminished sensitivity of insulin target tissues to healthy insulin levels." (PMID 36009236, 2022). "The authors also found that LVEF was positively correlated with the insulin sensitivity index in diabetic subjects, suggesting that cardiac insulin resistance was responsible for the reduction in LVEF and peak filling rate following insulin infusion." (PMID 35365882, 2022). "By recording FBG and serum insulin levels for HOMA-IR assessment, we found a significant decrease in insulin resistance in the SG group compared to the sham group." (PMID 36407319, 2022). "Insulin resistance results in decreased receptor substrate tyrosine phosphorylation (IRS), promoting insulin-activating signals." (PMID 36034954, 2022). "Other studies have indicated palmitic acid-induced impairment of insulin signaling in human Caco2/TC7 enterocytes and the involvement of PA in insulin resistance, thus contributing to metabolic diseases." (PMID 35566490, 2022). "ADF reduced fasting blood glucose level and homeostatic model assessment for insulin resistance (HOMA-IR), and improved insulin sensitivity." (PMID 35711339, 2022). "In normoglycemic humans with normal glucose tolerance, fasting insulin concentration alone has been reported to be as accurate as insulin:glucose ratio, HOMA, and Bennett index in documenting insulin resistance." (PMID 35968003, 2022). "Triglyceride to high-density lipoprotein cholesterol ratio (TG: HDL-C), Homeostatic Model Assessment for Insulin Resistance (HOMA-IR) and Single Point Insulin Sensitivity Estimator (SPISE) were calculated." (PMID 36589844, 2022). "Regarding insulin resistance based on established HOMA-IR threshold values, half of the patients were highly resistant (>5) and only 21 patients (15.2%) were sensitive to insulin (<2)." (PMID 36143268, 2022). "In T2DM, there is a link between reduced insulin signaling and peripheral nervous system (PNS) insulin resistance, resulting in damaged neurite outgrowth." (PMID 36615728, 2022). "Feeding rats with a high fructose diet, which is a commonly used model of insulin resistance, increased CSE expression and H2S production in the adipose tissue which correlated with impaired insulin-induced glucose uptake." (PMID 35625574, 2022). "Excessive DOC may impair the insulin signaling through oxidative stress and inflammatory mechanism, in DOC acetate(DOCA)+ salt hypertensive rats, oxidative and inflammatory transcriptions factors, such as NF-kB, AP-1, and JNK, which are implicated in insulin resistance are markedly elevated." (PMID 35937831, 2022). "Insulin during an oral glucose tolerance test (fasting, 30, and 120-min), overall insulin secretion index, insulinogenic index, HOMA-β, and HOMA-IR were main outcome measures for β-cell function and insulin resistance, respectively." (PMID 35077485, 2022). "Fasted CX mice had low glucose, insulin, HOMA-IR (homeostasis model assessment-estimated insulin resistance), and TGs in plasma compared to control mice." (PMID 36354755, 2022). "In addition, beside its positive impact on circulatory lipids, bariatric surgery is also known to improve insulin resistance and it has been demonstrated that androgenic hormones and insulin may be necessary for the growth and normal functioning of the meibomian gland." (PMID 35745192, 2022). "Increased inflammation, which develops under conditions of aging and the presence of cardiometabolic disorders, in contrast has an impact on suppression of insulin-mediated activation of the PI3K/Akt metabolic pathway, leading to insulin resistance." (PMID 35742902, 2022).
Insulin resistance (continued). "The homeostasis model of insulin resistance (HOMA-IR) is one of the most used indexes to estimate insulin resistance by assessing the fasting glucose and insulin levels." (PMID 36313112, 2022). "A mild increase in ketosis in peripheral blood, induced by a ketogenic diet, might improve peripheral insulin sensitivity, relieve hyperinsulinemia-related stress, reduce external insulin requirements, and inhibit its secretion, thereby improving glycemic profiles and mitigating insulin resistance." (PMID 36012064, 2022). "HFD feeding promoted insulin resistance in both genotypes when evaluated by HOMA-IR or ITT; however, SIRT2-KO mice were significantly more insulin resistant than WT mice." (PMID 35743232, 2022). "In diabetic mice and palmitate (PA)-induced insulin-resistant HepG2 and AML12 cells, BMP7 can inhibit the active of MAPKs to regulate insulin resistance." (PMID 35231067, 2022). "Another frequently used approach to determine IR is using the homeostasis model assessment of insulin resistance (HOMA-IR), which requires insulin levels for calculation." (PMID 36684574, 2022). "JNK signalling has been shown to regulate hepatic insulin sensitivity in NAFLD44, 45 and compound deletion of JNK1 and JNK2 in the liver improved glucose homeostasis and insulin resistance involving increased hepatic fatty acid β‐oxidation." (PMID 36101976, 2022). "Insulin resistance was calculated using the Homeostatic Model Assessment for Insulin Resistance (HOMA-IR) using fasting blood glucose and fasting insulin values." (PMID 35817936, 2022). "Herein, we observed that LDR strongly inhibited HFD-induced insulin resistance through PYCR1 activation to regulate insulin signalling, which is consistent with a previous report that inhibition of Akt/mTOR can induce insulin resistance." (PMID 36088469, 2022). "In obese subjects, circulating levels of this protein are significantly increased and positively correlated with adiposity indicators (BMI and percentage of fat), insulin resistance index (HOMA-IR), fasting glucose, and insulin levels." (PMID 35628332, 2022). "This study, through a robust methodology, demonstrated that the consumption of school feeding provided by Brazilian public schools has a protective effect on the variables related to insulin resistance, such as HOMA-IR, insulin, and blood glucose." (PMID 36078265, 2022). "At baseline, the postprandial FGF21 response was inversely correlated to insulin resistance as estimated by HOMA-IR, with more insulin resistant individuals exhibiting a larger postprandial decline in plasma FGF21 compared to insulin sensitive individuals." (PMID 36501091, 2022). "Here, HFD- and SRHFD-fed mice revealed similar insulin resistance (HOMA-IR, HFD = 8.6 vs. SRHFD = 11.7, p = 0.258) and insulin sensitivity scores (Matsuda Index, HFD = 2.6 vs. SRHFD = 2.3, p = 0.5972)." (PMID 35624726, 2022). "We alsoperformed oral glucose tolerance test (OGTT) and insulin tolerance tests (ITT).The results demonstrated that P4HA3 silencing increased oralglucose tolerance and improved insulin resistance in db/db mice." (PMID 35976267, 2022). "In this study, MOP supplementation reduced fasting blood glucose and fasting serum insulin in HFD-fed mice, indicating a positive effect of MOP on improving insulin resistance." (PMID 35548566, 2022). "Individuals with prediabetes have elevated levels of fasting serum insulin and Homeostatic Model Assessment for Insulin Resistance (HOMA-IR), indicating a direct relationship between prediabetes and insulin resistance." (PMID 36501195, 2022). "Insulin resistance (HOMA-IR) and beta-cell dysfunction (HOMA-Beta) were calculated from fasting insulin and glucose concentrations." (PMID 36313440, 2022). "Homeostasis model assessment-insulin resistance (HOMA-IR), an indirect index to measure insulin resistance based on the fasting glucose and insulin levels, was used and the values were comparable between the different acne severity groups." (PMID 36678524, 2022).
Insulin resistance (continued). "This suggested that insulin resistance is also crucial to LADA pathophysiology and provides a basis for the employment of insulin sensitizers such as thiazolidinedione in the treatment of LADA." (PMID 35837301, 2022). "Fasting serum insulin concentration and homeostatic model assessment for insulin resistance (HOMA-IR) were used as biomarkers of hyperinsulinemia (HI) and insulin resistance (IR)." (PMID 35012588, 2022). "In diabetic control rats, we found a significant rise in fasting serum insulin, FBG, and HOMA-IR, compared to normal control rats, demonstrating insulin resistance and glucose intolerance." (PMID 35964948, 2022). "The characteristics of SIRD were severe insulin resistance (the highest HOMA2-IR), more insulin secretion (the highest HOMA2-β), relatively high BMI, and late-onset age." (PMID 35966053, 2022). "In addition, side effects associated with the mTOR inhibitor rapamycin for DKD, such as hyperglycaemia, insulin resistance and dyslipidaemia, have also been reported, which may be related to the metabolic profile of the pancreas and other insulin-resistant tissues, including the liver and muscle." (PMID 36091814, 2022). "Previous research found that fasting plasma glucose and insulin levels significantly increased in HFD mice, and the increase was characterized by insulin resistance." (PMID 36235858, 2022). "Up-regulates insulin and leptin levels to down-regulate body weight, fat, GLU, Insulin resistance, GOT, GPT." (PMID 35548468, 2022). "Our data suggest that E2 replacement improves HFD‐induced insulin resistance, and this effect is accompanied by the alterations in the Akt2 and AS160 phosphorylation in insulin‐stimulated muscles of OVX rats." (PMID 35238495, 2022). "Next, we tested glucose and insulin tolerance in the Aid−/− and WT mice following HFDIO, demonstrating that the Aid−/− mice had IGT and insulin resistance." (PMID 35587276, 2022). "Because insulin suppresses the expression of these enzymes, it has long been assumed that patients with T2D have increased expression of PCK due to hepatic insulin resistance." (PMID 36360783, 2022). "Studies have shown that insulin resistance plays a key role in the in the progression of the MetS, so T1DM patients with MetS sustained losses of insulin and insulin resistance in the meantime." (PMID 36204109, 2022). "A phase 4 clinical trial completed in 2020 examined the relationship between insulin resistance and statin-induced T2DM using high-dose atorvastatin and was able to show increased insulin resistance and insulin secretion in the high-dose atorvastatin group." (PMID 35216514, 2022). "Insulin resistance is also present in T1DM, due, at least in part, to the presence of obesity, chronic hyperglycemia, and the exogenous administration of insulin." (PMID 36615728, 2022). "Firstly, the improvement of glucose metabolism (with a reduction of circulating glucose, insulin, and leptin levels) is favorable in obese subjects with CKD, often characterized by insulin resistance." (PMID 35811945, 2022). "Insulin release and thus HOMA-IR were significantly increased in HFD control mice indicating the likelihoods of development of insulin resistance in those subjects due to HFD feeding." (PMID 35707380, 2022). "The authors demonstrated that the greatest agreement with insulin sensitivity was with the Quantitative Insulin-sensitivity Check Index (QUICKI), followed by Homeostatic Model Assessment for Insulin Resistance, HOMA2-IR, and the Matsuda Index." (PMID 35887592, 2022). "Fasting glucose and insulin were measured at the time of OVX, and the homeostatic model assessment of insulin resistance (HOMA-IR) was calculated." (PMID 35725493, 2022). "Current treatments of insulin resistance or T2DM focus on promoting insulin sensitivity, improving islet β-cell function to enhance insulin secretion, or supplementing exogenous insulin." (PMID 36699697, 2022).